Y_RNA (Y RNA )
Gene: Miscellaneous RNA gene on chromosome 1 (248,045,788 to 248,045,889, forward strand). Ensembl gene ENSG00000200982.
Homologues: Orthologues: chimpanzee Y_RNA (98% identical), macaque Y_RNA (96% identical). Paralogues in human: Y_RNA (93% identical), Y_RNA (92% identical), RNY3 (91% identical), Y_RNA (91% identical), RNY3P1 (89% identical), Y_RNA (89% identical), Y_RNA (88% identical), Y_RNA (87% identical), Y_RNA (86% identical), Y_RNA (85% identical), RNY3P11 (84% identical), RNY3P14 (84% identical), and 97 more.